TMEM106C (transmembrane protein 106C)
Synonyms: MGC5576
Tractability: Antibody: UniProt predicts a signal peptide or a membrane-spanning region. PROTAC: ubiquitination databases record sites on it.
Gene: Protein-coding gene on chromosome 12 (47,963,569 to 47,968,885, forward strand). Ensembl gene ENSG00000134291.
Subcellular location: Endoplasmic reticulum membrane; Membrane
Gene Ontology:
Molecular function: protein binding
Cellular component: endoplasmic reticulum membrane; membrane
Genetic constraint (gnomAD): Loss-of-function variants: 26 observed, 31.24 expected, observed/expected ratio (o/e) 0.83, 90% interval 0.61 to 1.15. The upper end of that interval is the gene's LOEUF score, 1.15, which puts it in group 5 of 6, group 1 being the genes least tolerant of losing a copy. Missense variants: 278 observed, 316.51 expected, observed/expected ratio (o/e) 0.88, 90% interval 0.8 to 0.97. Synonymous variants: 119 observed, 122.21 expected, observed/expected ratio (o/e) 0.97, 90% interval 0.84 to 1.13.
Homologues: Orthologues: chimpanzee TMEM106C (99% identical), dog TMEM106C (91% identical), macaque TMEM106C (89% identical), guinea pig TMEM106C (88% identical), mouse Tmem106c (79% identical), rat Tmem106c (77% identical), zebrafish tmem106c (54% identical), tropical clawed frog tmem106c (49% identical).
Diseases named in the same sentence as TMEM106C in open-access papers:
TMEM106C is named in the same sentence as 12 diseases in open-access papers, as found by Europe PMC text mining. Sharing a sentence is not in itself a finding about the gene and the disease. The quoted sentences say what the papers report.
hepatocellular carcinoma (6 papers, 2021 to 2026). A malignant tumor that arises from hepatocytes. "A further example includes TMEM106C, which functions as an oncogene, and the upregulation of TMEM106C was associated with poor prognosis in hepatocellular carcinoma." (PMID 35991561, 2022). "For instance, TMEM106C was overexpressed in hepatoma tissues and strongly correlated with a poor prognosis, suggesting its involvement in the occurrence and progression of liver cancer." (PMID 37373430, 2023). "TMEM106C was overexpressed in hepatocellular carcinoma (HCC), and the inhibition of TMEM106C in liver cancer cell lines using small interfering RNA significantly suppressed the cell proliferation, migration, and invasion ability." (PMID 35392225, 2022). "Moreover, a higher expression level of TMEM106C was closely related to the malignancy of hepatocellular carcinoma (HCC)." (PMID 37367036, 2023). "Furthermore, the transcription level of TMEM106C in HCC was significantly higher in the subgroup analysis based on gender, age, ethnicity, disease stage and tumor grade, as revealed in 371 liver hepatocellular carcinoma (LIHC) samples in TCGA." (PMID 33591950, 2021).
ankylosing spondylitis (2 papers, 2014 to 2015). An autoimmune chronic inflammatory disorder characterized by inflammation in the vertebral joints of the spine and sacroiliac joints. "Human TMEM106C is a differentially expressed transcript in ankylosing spondylitis, and porcine TMEM106C was a positional and functional candidate for arthrogryposis multiplex congenita." (PMID 24975047, 2014).
glioma (1 paper, 2025). A benign or malignant brain and spinal cord tumor that arises from glial cells (astrocytes, oligodendrocytes, ependymal cells). "This suggests that while TMEM106C is upregulated in gliomas and associated with outcomes univariately, its prognostic effect is not independent of other factors." (PMID 41354084, 2025). "From the initial bioinformatics characterization, both TMEM106A and its paralog TMEM106C initially appeared significant in differential expression and survival analyses of glioma." (PMID 41354084, 2025). "Regarding TMEM106C, the all‐glioma, IDHwt, and Oligo groups exhibited significant differences, whereas the IDHmu group did not." (PMID 41354084, 2025). "For TMEM106C, only the all‐glioma group demonstrated an important difference, while the other subgroups did not." (PMID 41354084, 2025). "To comprehensively evaluate TMEM106A's role in glioma, we began by examining all its relatives from the entire TMEM106 family (including TMEM106A, TMEM106B, and TMEM106C) within the context of glioma." (PMID 41354084, 2025).
Neurodegeneration (1 paper, 2025). Progressive loss of neural cells and tissue. "The mutation of the TMEM106B gene on Chromosome 7, a homolog of TMEM106C, is a risk factor of neurodegeneration disease." (PMID 41153414, 2025).
tumor (5 papers, 2021 to 2025). "The mRNA and protein level of TMEM106C were overexpressed in HCC tumor tissues and cell lines HepG2 and SMMC-7721." (PMID 37367036, 2023). "Based on the GEPIA database, we initially discovered that TMEM106C is highly expressed in HCC tumor tissues compared to normal liver tissues (P < 0.01)." (PMID 33591950, 2021). "The higher transcription level of TMEM106C was almost parallel to that of tumor stage and tumor grade, indicating that TMEM106C is closely related to the malignant biological behavior of HCC." (PMID 33591950, 2021). "The upregulation of TMEM106C was correlated with tumor stage and prognosis of HCC." (PMID 37367036, 2023). "Upregulation of TMEM106C was closely correlated with sex, tumor stage, tumor grade and prognosis." (PMID 33591950, 2021). "Comprehensive differential expression analysis between normal and tumor tissues revealed complex regulatory patterns of stem cell marker genes, with key genes such as TMEM106C, ECT2, PSMD2, STIL, and TTK showing significant upregulation in tumor tissues." (PMID 40766320, 2025). "Among these, key genes including TMEM106C, ECT2, PSMD2, STIL, and TTK showed significant upregulation in tumor tissues, and their high expression may be closely associated with abnormal activation of tumor stem cells, cell cycle regulation, and enhanced self-renewal capacity." (PMID 40766320, 2025). "Therefore, in our study, we conducted experiments using fresh HCC tumor tissues and HCC cell lines to confirm the expression level of TMEM106C." (PMID 33591950, 2021). "However, the TMEM106C transcripts of stage 4 and grade 4 were not significantly different from those of the other stages, which may be due to the small sample size or the influence of tumor microenvironment." (PMID 33591950, 2021).
cancer (2 papers, 2021). A tumor composed of atypical neoplastic, often pleomorphic cells that invade other tissues. "Taken together, these results suggest that TMEM106C plays a significant role in the regulation of cellular proliferation and cancer cell motility." (PMID 33591950, 2021). "Furthermore, as illustrated by the transwell assay with or without Matrigel, overexpression of TMEM106C obviously promoted the migration and invasion ability of cancer cells compared with the NC group, while low expression of TMEM106C impaired this effect (**P < 0.01)." (PMID 33591950, 2021). "The upregulation of TMEM106C predicts poor HCC prognosis and enhances the malignancy of cancer cells." (PMID 34659569, 2021). "Third, the network of TMEM106C in HCC is derived from RNA sequencing data and existing studies of HCC or other kinds of cancers; hence, further validation is still needed to authenticate the potential mechanisms of TMEM106C in HCC." (PMID 33591950, 2021). "Compared with their noncancerous counterparts, the levels of TMEM106C were much higher in cancer tissues." (PMID 33591950, 2021).
TMEM106C also shares sentences with these, for which no sentence is quoted: liver cancer (5 papers); arthrogryposis (1); astrocytomas (1); glioblastoma (1); neuroblastoma (1); oligodendroglioma (1).